IL6R (interleukin 6 receptor)
Diseases named in the same sentence as IL6R in open-access papers (continued):
Sharing a sentence is not in itself a finding about the gene and the disease.
COVID-19 (continued). "More recently, the REMAP-CAP trial has shown the benefit of anti-IL6R therapy when given to critically ill patients on admission to intensive care units, indicating that IL6 does contribute to critical illness from COVID-19." (PMID 33704068, 2021). "Protein-protein docking between COVID-19-Spike and IL6 receptor (IL6R)/IL6/IL6 receptor subunit beta (IL6ST) was simulated to verify whether IL6, the core target identified through our network pharmacology-based approach, was a pathogenic target." (PMID 34731090, 2021). "The PBMC of adult COVID-19 patients treated (n = 12) or not (n = 4) by Tocilizumab, an anti-IL-6R mAb drug, had similar cell counts of total γδ T lymphocytes (on average 59 vs. 45 γδ T cells per sample, respectively), as for both TCRVγ9 and TCRVγnon9 subsets." (PMID 34835019, 2021). "Two proteins, called IL-6R and FAS, were involved in the immune response and could be responsible for the immune over-activation often seen in severe COVID-19." (PMID 34402426, 2021). "Our results showed 13 potential targets of biochanin A; the molecular interaction network analysis using Cytoscape further highlighted the involvement of six core targets of biochanin A, EGFR, CCND1, IL2, IL1A, IL6R, and PPARG, for the treatment of CRC/COVID-19." (PMID 34931923, 2021). "The results of CORONA study are important and contribute to the data about the effects of anti-IL6R therapy in severely but not critically ill COVID-19 patients." (PMID 34586459, 2021). "As studies in sepsis have indicated the TREM-1 pathway as a potential therapeutic target, it is tempting to speculate that, like anti-IL-6R therapy, a beneficial effect of TREM-1 modulation in patients with COVID-19 could be also present." (PMID 34195785, 2021). "Tocilizumab, a humanized anti-IL-6R antibody approved for the treatment of rheumatoid arthritis, CRS, and idiopathic multicentric Castleman disease (IMCD), is recommended for the treatment of COVID-19-induced CRS." (PMID 33240265, 2020). "Inhibition of IL-6 related signalling pathways via blocking IL-6 or IL-6 receptors (IL-6R) is a promising approach to prevent CRS/cytokine storm syndrome and rapid, severe, and serious deterioration during SARS-CoV-2 infection and transition to COVID-19." (PMID 32668803, 2020). "Drugs that inhibit IL-6, IL-6R and JAK signaling (activated by IL-6 family members) are FDA-approved for the treatment of rheumatoid arthritis and other inflammatory conditions and are currently being evaluated in patients with COVID-19." (PMID 32629875, 2020). "Another anti-IL-6R antibody, SAR, used for rheumatoid arthritis, has been tested in a multicenter, double-blind, clinical phase II/III study in patients with severe COVID-19 (NCT04315298)." (PMID 33014208, 2020). "Although evidence from randomized, double-blinded clinical trials is still lacking, the IL-6R inhibitor tocilizumab (TCZ) has shown some clinical benefits in the treatment of severe COVID-19 patients and have been included in clinical guidelines." (PMID 33195318, 2020). "Therefore, our findings do not support the idea that early interleukin-6 receptor blockage is a successful therapeutic approach in critically sick COVID-19 hospitalized patients." (PMID 36833140, 2023). "Several antiviral drugs (PaxlovidTM, Remdesivir, Bebtelovimab, Molnupiravir, Andrographis) and immune modulators (Olumiant, an interleukin-6 receptor blocker) were approved by drug regulatory authorities for use against COVID-19 for treating non-hospitalized or hospitalized COVID-19 patients." (PMID 37765004, 2023). "Thus, in the early stages of COVID-19, in which IL-6 plays protective roles, IL-6R inhibition would not be helpful but would be detrimental." (PMID 37818368, 2023).
COVID-19 (continued). "First, we studied the circulating levels of IL-1α, IL-1β, IL-18, IL-15, IL-12p40, IL-12p70, IL-6, IL-27, IL-1Ra, IL-1RI, IL-1RII, IL-6R and sgp130, which are innate proinflammatory cytokines, and their receptors in survivors and non-survivors of severe COVID-19 and healthy controls." (PMID 36142255, 2022). "Thus, IL-6R represents an excellent therapeutic target; IL-6R-blocking mAbs such as tocilizumab and sarilumab have been included in the NIH COVID-19 Treatment Guidelines indicated in hospitalized adults that require oxygen delivery through a high-flow device or noninvasive ventilation." (PMID 35631442, 2022). "The Omicron variant has numerous mutations in the spike protein (S-gene), and drugs used in severe COVID-19 cases such as corticosteroids and interleukin-6 receptor blockers may not effectively target the spike protein in severe Omicron." (PMID 35326916, 2022). "While studies on the efficacy of chemoimmunotherapy in NSCLC complicated by COVID-19 are limited, one case reports a NSCLC patient on a combination of carboplatin/pembrolizumab/pemetrexed who developed COVID-19 pneumonia and responded well to anti-interleukin 6 receptor tocilizumab." (PMID 35600364, 2022). "In early stages of COVID-19, in which IL-6 may play protective roles, IL-6R blockade would not be useful either." (PMID 35340805, 2022). "Tocilizumab, an interleukin-6 receptor blocker, has been used in the inflammatory phase of COVID-19, but its impact independent of corticosteroids remains unclear in patients with severe disease." (PMID 33831046, 2021). "Considering that the anti-IL-6R antibody (tocilizumab) is an effective treatment for cytokine release syndrome in CAR-T cell therapies 28,36, researchers might want to consider drugs with a similar mechanism of action in COVID-19 treatment." (PMID 33390771, 2021). "Anti-IL-6R antibodies such as tocilizumab (NCT04322773) or sarilumab (NCT04359901; NCT04357808), and the anti-IL-6 antibodies clazakizumab (NCT04348500; NCT04381052; NCT04343989; NCT04381052) and olokizumab (NCT04380519) are currently in clinical trials for COVID-19 patients." (PMID 33324210, 2020). "IL6R and IL6ST genes, respectively, in 227 COVID-19 patients (132 hospitalized and 95 non-hospitalized)." (PMID 37243282, 2023). "Moreover, due to the absence of data, our study did not consider or analyze the baseline levels of IL-6; therefore, we could not illustrate the specific function of IL-6/IL-6R/JAK pathway antibodies on patients with COVID-19 with different baseline IL-6 levels." (PMID 33384605, 2020). "This post hoc analysis of plasma lipid samples from hospitalized patients with severe-to-critical COVID-19 shows that a marked HDL-C depression is dependent on disease severity and, overall, is not responsive to anti-inflammatory intervention with an IL-6R monoclonal antibody." (PMID 38795859, 2024). "Altogether, COVID-19 patients characterised by serum ferritin levels > 1600-2000 ng/mL, LDH > 500-550 U/L, and D-dimer > 3000-5000 ng/mL, are most likely hyperinflamed and critically-ill patients who do not respond to IL-6R blockade (but may still respond to IL-1 blockade)." (PMID 35340805, 2022).
rheumatoid arthritis (248 papers, 2010 to 2026). A chronic, systemic autoimmune disorder characterized by inflammation in the synovial membranes and articular surfaces. "Tocilizumab (TCZ, which globally blocks IL-6 activities through IL-6R-α and sIL-6R), when used in treating rheumatoid arthritis, is associated with adverse cardiovascular events and an increase in serum cholesterol, which increases cardiovascular risk." (PMID 39063055, 2024). "Multiple studies have linked variations in the IL6R gene to several conditions, including multiple sclerosis (MS), rheumatoid arthritis (RA), type I diabetes (T1D), IBD and AS in multiple studies." (PMID 38822340, 2024). "For instance, in rheumatoid arthritis, the presence of the AA genotype of rs12083537 (IL-6R gene) was associated with a better response to tocilizumab, which targets IL-6 receptors." (PMID 37511413, 2023). "Patients with rheumatoid arthritis are potentially at risk of decreased efficacy of drugs with a narrow therapeutic index during the first weeks of anti-IL-6R therapy." (PMID 37831074, 2023). "This study was conducted to investigate possible associations between six different SNPs in the IL6R gene and treatment response outcomes in patients with rheumatoid arthritis treated with sarilumab over a 6-month period." (PMID 38001504, 2023). "Tocilizumab, an IL-6R antibody, is clinically used in the treatment of various autoimmune diseases, such as rheumatoid arthritis, which is associated with pathologically hyper-activated IL-6 signalling." (PMID 36429126, 2022). "Clinically, human studies showed that in patients with rheumatoid arthritis who received the interleukin-6 receptor antagonist, the risk of myocardial infarction and stroke can be decreased." (PMID 34943061, 2021). "IL6R rs4537545T* allele is also associated with C-reactive protein, allergic disease, rheumatoid arthritis and coronary artery disease." (PMID 33517400, 2021). "In humans, the systemic treatment with tocilizumab, the blocking anti-IL-6R antibody approved for treatment of rheumatoid arthritis, has also been shown to increase the risk to respiratory virus infection." (PMID 33193346, 2020). "GWAS’s have related IL6R to immune diseases and associated traits, including coronary heart disease, pulmonary function, asthma, C-reactive protein, rheumatoid arthritis and IBD susceptibility." (PMID 28129359, 2017). "IL-6 trans-signaling, which is mediated via the s-IL-6R, is critically involved in several inflammatory and autoimmune diseases including inflammatory bowel disease, rheumatoid arthritis, and asthma, as well as colitis-associated cancer." (PMID 26091352, 2015). "Female-biased genes were enriched for genes linked to rheumatoid arthritis, including the gene IL6R, which is a well-known target in rheumatoid arthritis treatment." (PMID 24438232, 2014). "Plasma-soluble IL6R levels have been shown to be positively associated with the number of C alleles in rheumatoid arthritis patients." (PMID 22128229, 2011). "Regardless, disruption of the IL-6 axis (including IL-6R and gp130), and in turn, the production of acute phase cytokines, has been implicated in multiple chronic inflammatory conditions, including rheumatoid arthritis (RA), systemic lupus erythematosus (SLE), and psoriasis." (PMID 40497942, 2025). "Based on sparse data from three patients, continuous anti-IL-6R therapy seems to cause an acute but transient increase in CYP3A4 activity in rheumatoid arthritis patients, which may be due to a normalization of the inflammation-suppressed CYP activity." (PMID 37831074, 2023). "These IL6R variants are associated with rheumatoid arthritis and with coronary artery disease in the same direction, suggesting that interleukin-6 receptor inhibition may also reduce risk of cardiovascular disease." (PMID 36736292, 2023).
rheumatoid arthritis (continued). "Rheumatoid arthritis and periodontitis are known to be directly associated and a study of 55 patients diagnosed with rheumatoid arthritis and chronic periodontitis first showed improved periodontal conditions after 20 months of medication with Il-6R antagonists." (PMID 37342352, 2023). "Despite being regulated by the same molecular mediators, IL-6 and IL-6R, the IL-6 trans-signaling pathway promotes activation of immune responses and it is associated with the development of several inflammatory diseases, including rheumatoid arthritis." (PMID 33579029, 2021). "Indeed, a coding variant in IL6R that alters circulating sIL-6R concentration is associated with impaired IL-6 signalling and the protection from cardiovascular disease, rheumatoid arthritis and T1D45." (PMID 25965853, 2015). "Tocilizumab, a monoclonal antibody targeting the interleukin-6 receptor (IL6R), is licensed for treatment of rheumatoid arthritis, but whether IL6R blockade reduces risk of coronary heart disease is unknown." (PMID 22421340, 2012). "In this case, rheumatoid arthritis (RA) patients are treated with Tocilizumab, a competitive antagonist that targets the interaction between IL-6 and a soluble variant of its receptor IL-6R (sIL-6R)." (PMID 39125692, 2024). "TCZ, an IL-6R antibody (Ab) that globally blocks IL-6 activities through IL-6R-α and sIL-6R, is associated with a significant reduction in the QTc interval in patients with rheumatoid arthritis (RA)." (PMID 39125976, 2024). "Increased plasma IL-6 levels and association with the IL-6 receptor (IL-6R) risk alleles are reported in connective tissue diseases (CTDs) known to cause pulmonary hypertension, such as rheumatoid arthritis (RA)." (PMID 34588193, 2022). "Further, in contrast to the increasing effect of IL-6R inhibition in patients with rheumatoid arthritis, the effect of tocilizumab on LDL levels in both NSTEMI and STEMI patients treated with tocilizumab were limited." (PMID 41543641, 2026). "An approximately 10% increase in triglycerides (TG) and LDL cholesterol was observed in patients with rheumatoid arthritis receiving anti-IL-6R treatment by tocilizumab." (PMID 41543641, 2026). "One of the popular antibodies on the market, Tocilizumab, targets IL-6Rα to treat rheumatoid arthritis, juvenile idiopathic arthritis, and Castleman disease." (PMID 40733185, 2025). "Sarilumab is an approved drug for rheumatoid arthritis and Castleman disease that targets IL-6Rα, while Vobarilizumab is undergoing phase 3 clinical trials for rheumatoid arthritis." (PMID 40733185, 2025). "Vobarilizumab (ALX-0061) was intended to eliminate symptoms of rheumatoid arthritis and systemic lupus erythematosus by blocking the interleukin-6 receptor." (PMID 41009364, 2025). "Clazakizumab and siltuximab directly target the site I of IL-6 for interfering the formation of IL-6 and IL-6R complex, and have been approved for the effectiveness in the treatment of rheumatoid arthritis (RA) and Castleman’s disease in clinical trials." (PMID 38890694, 2024). "Currently, tocilizumab, a humanized anti-human interleukin-6 receptor (IL-6R) antibody, is widely used in autoimmune diseases such as rheumatoid arthritis." (PMID 39664374, 2024). "Although IL-6 is a pro-inflammatory cytokine and its levels are very high in processes involving an inflammatory response (including autoimmune diseases like rheumatoid arthritis), IL-6 can also exhibit anti-inflammatory effects via the membrane-bound IL-6R." (PMID 39007140, 2024). "The use of IL-6 or IL-6r inhibitors, such as sarilumab or tocilizumab, is approved for the treatment of immune related toxicities, autoimmune diseases such as arthritis rheumatoid, and of cytokine release syndrome from CAR-T or Tebentafusp." (PMID 38443899, 2024). "TCZ, a monoclonal antibody against the interleukin 6 receptor, has demonstrated efficacy in reducing disease activity and ameliorating symptoms in rheumatoid arthritis patients." (PMID 39310504, 2024).
rheumatoid arthritis (continued). "Tocilizumab is a monoclonal antibody against IL-6R including sIL-6R and IL-6/sIL-6R complex and it has been approved for the treatment of rheumatoid arthritis and cytokine release syndrome." (PMID 38541674, 2024). "At the same time, IL-6R blockade has been shown to improve insulin sensitivity in non-diabetic patients receiving tocilizumab for management of rheumatoid arthritis." (PMID 39723211, 2024). "Phase I/II clinical study Toxicity, pharmacokinetics, and dose-finding study of repetitive treatment with the humanized anti-interleukin 6 receptor antibody MRA in rheumatoid arthritis." (PMID 37503097, 2024). "Tocilizumab, an IL-6Rα mAb originally FDA-approved for rheumatoid arthritis, is being investigated in combination with trastuzumab and pertuzumab for the treatment of metastatic trastuzumab-resistant HER2-enriched breast cancer (NCT03135171)." (PMID 39768178, 2024). "Based on the primary endpoint midazolam metabolic ratio, we observe a slight trend towards a weak increase in CYP3A4 activity in patients with rheumatoid arthritis after 3 weeks of anti-IL-6R therapy." (PMID 37831074, 2023). "TCZ is a fully humanized anti-IL-6R antibody approved as therapy for numerous autoimmune diseases, including rheumatoid arthritis (RA), adult-onset Still’s disease, and Castleman disease, as well as for the treatment of systemic JIA, where uveitis is uncommon." (PMID 36979992, 2023). "Tocilizumab is monoclonal antibody targeting IL-6R that has been approved to treat rheumatoid arthritis." (PMID 36635302, 2023). "This study aimed to prospectively assess the activity of six CYP enzymes in patients with rheumatoid arthritis before and after 3 and 12 weeks of continuous anti-IL-6R therapy." (PMID 37831074, 2023). "Clinical studies have shown a > 50% lower simvastatin (CYP3A4 substrate) exposure 1 week after a single anti-IL-6R dose in patients with rheumatoid arthritis, indicating a normalization (increase) in CYP3A4 activity." (PMID 37831074, 2023). "For instance, tocilizumab, targeting the IL-6R, is approved for rheumatoid arthritis, juvenile idiopathic arthritis, and Castleman disease, while sarilumab, also targeting the IL-6R, is in late-stage clinical trials." (PMID 37759507, 2023). "Second, we included rheumatoid arthritis patients with a clinical indication for anti-IL-6R therapy; thus, the results are generalizable to the intended population." (PMID 37831074, 2023). "In rheumatoid arthritis patients treated for 12 months with tocilizumab, an anti-interleukin-6 receptor monoclonal antibody that rapidly reduces acute phase reactants, C3 and C4 serum levels also decrease." (PMID 36983904, 2023). "Tocilizumab blocks the IL-6 receptor (IL-6R) and is approved in more than 100 countries worldwide for the treatment of rheumatoid arthritis (RA) and juvenile idiopathic arthritis (JIA)." (PMID 37895153, 2023). "In contrast, IL-6 antibodies failed in phase II clinical trials for IBD due to non-tolerable side effects, including intestinal perforations which were also observed for anti-IL-6R therapy for rheumatoid arthritis." (PMID 37838173, 2023). "Blockade of IL-6R with monoclonal antibodies such as tocilizumab is a long-established treatment of rheumatoid arthritis to reduce systemic and articular inflammation." (PMID 37342352, 2023). "Some cell types expressed different rheumatoid arthritis genes in different subsets of cells (for example, LEF1 in CTAP-TF-associated naive states and IL6R in CTAP-TB-associated TFH/TPH states)." (PMID 37938773, 2023). "In 2009, the first humanized IL-6 receptor antagonist (anti-IL-6R) monoclonal antibody, tocilizumab, was approved by the European Medicines Agency for the treatment of rheumatoid arthritis." (PMID 37831074, 2023). "Sarilumab, an FDA-approved anti-IL-6R antibody for rheumatoid arthritis, which blocks both mIL-6R and sIL-6R, is currently under clinical studies for breast cancer." (PMID 35924148, 2022).